TNF (tumor necrosis factor)
Diseases named in the same sentence as TNF in open-access papers (continued):
Sharing a sentence is not in itself a finding about the gene and the disease.
colon carcinoma (continued). "Therefore, we used TNF-α stimulation to potentiate the malignant phenotype of colon cancer cells in this study." (PMID 32230772, 2020). "In addition, CyCl suppressed nuclear factor-kappa B (NF-κB) signaling and induced the activation of the nuclear factor erythroid 2-related factor 2 (Nrf2) pathway in tumor necrosis factor-alpha (TNF-α)-stimulated colon cancer cells." (PMID 32230772, 2020). "In the present study, the results showed that JK5G treatment could significantly inhibit the growth of colon tumors, as well as the levels of cytokines in serum, such as IL-2, IL-6, and TNF-α." (PMID 33178591, 2020). "Indeed, it has been found that infiltrating macrophages secrete inflammatory mediators CCL2, IL-1α, IL-6, and tumor necrosis factor-α (TNF-α) to promote the proliferation of colon cancer cells." (PMID 33224886, 2020). "Overall, our data indicate that colon cancer-associated ADAM17 variants (E319G, E406X, M435I) exhibit diminished substrate recognition and/or enzymatic activity towards physiological substrates of the metalloprotease (TNFα, IL-6R, AREG)." (PMID 33143292, 2020). "If TNF-α-initiated inflammation is left unresolved, it may lead to colon cancer through angiogenesis and cell invasion." (PMID 32422882, 2020). "Interestingly, antigen-specific CD8+ T cells used TNF as part of their anti-tumor effector arsenal to kill MC38 mouse colon carcinoma cells." (PMID 31417576, 2019). "Besides, we also found that Lactobacillus acidophilus reduced inflammation in lipopolysaccharide (LPS)- and tumor necrosis factor alpha (TNF-α)-induced inflammatory colon cancer cells." (PMID 31905929, 2019). "Moreover, TNF signaling has been shown to drive colonic tumor formation after sustained chronic colitis." (PMID 31316505, 2019). "TNF-α was shown to promote colon cancer cell migration and invasion." (PMID 31608109, 2019). "TNF-α was suggested to be a prominent effector of colon cancer development." (PMID 29992185, 2018). "Moreover, 10-hydroxy-2-decenoic acid, the major lipid constituent in RJ, was found to exert anti-inflammatory effects in human colon cancer cells via inhibiting NF-κB, which further suppressed the release of IL-1β and TNF-α." (PMID 30544760, 2018). "Moreover, peritoneal liquids harvested after colectomy–from cancer and non-cancer conditions–induced the in vitro migration capacity of colon cancer cell lines, and this effect correlated with increased levels of TNF-α and IL-10 in the samples." (PMID 29462209, 2018). "In conclusion, our study shows that MK2 activity in colon tumors and colon tumor-associated macrophages is a critical regulator of not only IL-1β, IL-6, and TNF-α but also MMM, which has not previously been reported." (PMID 30298062, 2018). "In this study, co-culture of C2C12 myotubes with CT26 colon carcinoma cells increased TNF-α and myostatin concentrations in the medium and altered the metabolism of C2C12 myotubes, indicating that these two types of cells interact with each other via secreted factors." (PMID 29069832, 2017). "Caco-2 and HT-29 human colon cancer cells were stimulated with TNF-α at 50 ng/ml for 2h and 24h." (PMID 29285251, 2017). "Given that TNF-α is known to induce colon cancer cell death both in vivo and in vitro, we hypothesize that this cytokine, by inducing death of transformed cells, might be related with jacalin's chemopreventive effect." (PMID 28676858, 2017). "Indeed, this idea is supported by a previous study that showed that SOCS3 overexpression in a colon cancer cell line inhibits subsequent TNF-induced p65 phosphorylation." (PMID 28193827, 2017). "To test this hypothesis, we first examined the effect of conditional medium collected from inactivated or TNF-α-activated hMSCs (conditional media (CM)/TCM) on colon cancer cell growth." (PMID 28542126, 2017).
colon carcinoma (continued). "In our experimental study it was not possible to associate the effect of fructans in colon cancer with the role of microorganisms in the small intestine; however, we studied the possible action mechanism involved in TNFα and IL-10 concentration." (PMID 28293641, 2017). "Indeed, S1P production is increased in colon cancer, and S1P is required for TNF alpha (TNFα)-dependent nuclear factor-kappa B activation (NF-κB)." (PMID 28362332, 2017). "Furthermore, in vitro studies with the addition of type-2 macrophage medium, TNFα or LTD4 to colon cancer cells also induced nuclear accumulation of β-catenin and increased invasiveness." (PMID 28410235, 2017). "Similar data were obtained in human colon cancer cells Caco-2 and HT-29 treated with TNF- α." (PMID 29285251, 2017). "Notably, AK301 was found to arrest colon cancer cells in a mitotic state that was acutely sensitive to TNF." (PMID 27097159, 2016). "Thus, we compared the production of cytokines such as IFN-γ, IL-17, and TNF-α, which were known to have anti-cancer activity, between colon cancer patients and healthy controls." (PMID 27517754, 2016). "By contrast, conditioned medium of EGFR knockout colon cancer cells inhibited expression of these M2-related markers and induced macrophage expression of the M1-related markers inducible nitric oxide synthase (iNOS), IL-12, TNF-α and CCR7." (PMID 27683110, 2016). "Peritoneal fluids collected at surgery initiation and after surgery were evaluated for their effect on migration potential of human colon cancer cells using an in vitro scratch assay and on TNF-α, IL-1β, IL-6, and IL-10 levels using bead-based fluorokine-linked multianalyte profiling." (PMID 26819599, 2016). "Colon cancer migration capacity was partly correlated with TNF-α and IL-10." (PMID 26819599, 2016). "IFNγ and TNFα synergistically induce iNOS expression in human colon carcinoma cells." (PMID 26497740, 2015). "In addition, TNF-α-induced signaling can be detected in single cells isolated from colonic crypts, as well as from colonic tumors using flow cytometry following DISSECT." (PMID 26519361, 2015). "Interrupting tumor cell-macrophage communication by targeting TNF-α may provide an alternative therapeutic approach for the treatment of colon cancer." (PMID 26556872, 2015). "In addition, AURKA inhibition, using specific or pan Aurora kinase inhibitors, sensitized colon cancer cells to chemotherapy, TNF or TRAIL induced apoptosis as well as mitotic failure and cell death when inhibited along with SRC." (PMID 25987188, 2015). "Therefore, in the current study we investigated the impact of 1,25D3, tumor necrosis factor alpha (TNFα), and interleukin (IL)-6 on CaSR expression in a differentiated (Caco2/AQ) and in a moderately differentiated (Coga1A) colon cancer cell line." (PMID 24176760, 2014). "We are the first to show in a colon cancer cell line, that TNFα inhibits CYP27B1 transcription." (PMID 24120915, 2014). "We have shown that nuclear β-catenin translocation protects colon cancer cells from TNF-induced cell death, which may have an important role in chronic intestinal inflammation." (PMID 23967107, 2013). "Numerous studies have verified the level of IL-1β and TNF-α in human colon cancer." (PMID 23379788, 2013). "TNF-α, a vital cytokine produced by the inflammatory response has previously been reported to increase transcription of Nox1 and increase superoxide production in colon cancer cells after 24 hours." (PMID 23071493, 2012). "However, we found no change in leukocyte infiltration in tumors over-expressing IL-17F despite the elevated levels of IL-6 and TNFα in vitro, and unaltered cytotoxic immune cell frequencies in mesenteric lymph nodes of colon tumor bearing Il-17f−/− mice." (PMID 22509371, 2012). "Consequently, TRAIL therapy in combination with TNFα/IFN-γ-producing CTL adoptive transfer immunotherapy effectively suppressed colon carcinoma metastasis in vivo." (PMID 21264227, 2011).
colon carcinoma (continued). "Our data thus suggest that blocking NF-κB activity might increase human colon carcinoma cells to IFN-γ/TNFα-sensitized and TRAIL-induced apoptosis." (PMID 21264227, 2011). "Likewise, the AS-ODN enhanced TNF-α-induced cell death in colon carcinoma cell lines, which showed significant level of cytosolic Hsp60." (PMID 20351780, 2010). "We have observed that human colon cancer cells (HT-29) are able to secrete granulocyte-macrophage-colony stimulating factor, granulocyte-colony stimulating factor and macrophage-colony stimulating factor when stimulated with cytokines (IL-1β and TNF-α)." (PMID 11953891, 2002). "The prior literature review gave the research statement which helped us to draw the experiment where we could contemplate on the pivotal role of TNF-α and NF-kB regulation in the skin and colon cancer cell lines under the influence of Argemone mexicana (Linn) crude extract." (PMID 39687882, 2024). "The current results demonstrated elevated levels for TNF-α (376.2 ± 20.9 vs. 94.8 ± 18.3) and NFκB (3,287.7 ± 264.7 vs. 724.5 ± 79.1) and for the downstream products IL-1β (446.9 ± 23.3 vs. 85.25 ± 13.5) and IL-6 (258.0 ± 34.7 vs. 20.7 ± 9.8) in the colon cancer group versus the saline group." (PMID 38645563, 2024). "Furthermore, the protein levels of PCNA protein (a marker for cell proliferation), cyclin D1 and cyclin E (key regulators of the cell cycle), and MMP-9 (a key regulator of metastasis in colon cancer), as well as TNFα (a marker for extrinsic cell apoptosis) in nude mice were measured by IHC." (PMID 36979011, 2023). "Moreover, the results of regression analysis showed that the risk of death in elderly patients with colon cancer increased with the increase of serum TNF-α and IL-6 levels, indicating that TNF-α and IL-6 are independent risk factors for poor prognosis in elderly patients with colon cancer." (PMID 37430251, 2023). "Similarly, BRD4 inhibition led to expression of proinflammatory genes such as Baculoviral IAP Repeat Containing 2 & 3 (BIRC2 and BIRC3), which in turn led to tumor necrosis factor (TNF) production triggering apoptosis in preclinical colon cancer models, boosting anti-tumour immunity." (PMID 36551637, 2022). "To determine whether sorghum bran extracts (HP, SC, and Sumac) inhibit the TNF-α-stimulated NF-κB pathway, we transfected NF-κB luciferase reporter genes into human colon cancer cells and treated with 2.5 mg/mL of sorghum extracts in the presence or absence of TNF-α." (PMID 34361052, 2021). "In addition, astragalin significantly downregulated the expression of key proteins in the NF-κB signaling pathway and inhibited the transcriptional activity of NF-κB P65 stimulated with inflammatory cytokines TNF-α, thereby inhibiting the growth of colon cancer cells in vitro." (PMID 33953676, 2021). "Moreover, TNF-α-induced phosphorylation of IκBα and IKKα/β, characteristics of canonical NF-κB signal activation, was dramatically inhibited by the treatment with CyCl in colon cancer cells." (PMID 32230772, 2020). "This is of great importance considering the results of a recent study in mice xenografted with human colon cancer cells, suggesting that tumor necrosis factor (TNF) inhibition combined with CTLA-4 and PD-1 immunotherapy may provide a clinically feasible prophylactic strategy regarding some irAEs." (PMID 32325840, 2020). "Thus, in colon cancer patients infected with F. nucleatum, an important increase on TNF-α and IL-10 expression levels have been shown in adenomas, a precursor lesion of colon cancer; while into tumor, IL-6 and IL-8 increased levels were induced by F. nucleatum." (PMID 31662752, 2019). "TNF in the next group, high singling levels could be important in colon cancer." (PMID 30774816, 2018).
colon carcinoma (continued). "Moreover, there was also a decrease in levels of inflammatory cytokines TNF-α, IL-1β, IL-6, and IL-17A in the sera or colon tissues of Trim27−/− mice, which was consistent with the decreased inflammatory cell infiltrations in colon tumors of Trim27−/− mice." (PMID 30143645, 2018). "Besides macrophage from tumor microenvironment, TNF-α could also be produced in tumor cells including like B-cell lymphoma and breast and colon carcinoma." (PMID 29238068, 2017). "Furthermore, TNF was found to play a key role in the colon cancer promoting effect of obesity." (PMID 28492497, 2017). "While screening for molecules that might be able to accentuate colon cancer cell sensitivity to the inflammatory microenvironment of a cancer, we identified a family of small molecule inhibitors that dramatically enhanced colon cancer cell death in the presence of TNF and related death ligands." (PMID 27097159, 2016). "Therefore, in the present study, we studied the impact of 1,25D3, TNFα, and IL-6 on transcriptional and translational regulation of CaSR in two colon cancer cell lines with different proliferation and differentiation properties, mimicking different tumor stages." (PMID 24176760, 2014). "Thus, TNFα may simultaneously activate apoptosis and cell survival pathways, two conflicting biological processes, in human colon carcinoma cells." (PMID 21264227, 2011). "Therefore, we reasoned that use of adoptive transfer of tumor-specific CTLs to produce IFN-γ and TNFα locally in the tumor microenvironment in combination with TRAIL protein/mAb therapy should effectively induce colon carcinoma cell apoptosis, and thereby suppressing colon cancer metastasis." (PMID 21264227, 2011). "Therefore, we reasoned that IFN-γ and/or TNFα might also mediate the intrinsic apoptosis pathway to sensitize colon carcinoma cells to TRAIL-induced apoptosis." (PMID 21264227, 2011). "As CPT-11 treatment resulted in an increase in TNFα intratumoural concentration and as AS602868 revealed the apoptotic potential of TNFα in HT-29 colon cancer cells as well as in Jurkat leukaemic cells, this mechanism could also be involved in AS602868/CPT-11 antitumoural effect." (PMID 18182997, 2008). "In the present study we confirm our previous observations that human colon cancer epithelial cells have the ability to produce GM-CSF, G-CSF and M-CSF in response to cytokines commonly found in the inflammatory responses (IL-1β and TNF-α), including those that accompany tumour formation." (PMID 11953891, 2002). "adolescentis SPM0212 reduced the growth of colon cancer cell lines (Caco-2, HT-29, and SW480) and enhanced the TNF-α release." (PMID 41237260, 2025). "In comparison to the CK group, except for the individual cultivation of mouse colon cancer cells with Lactobacillus LAB35, the mRNA expression of the TNF‐α gene is downregulated in all other treatment groups." (PMID 39723039, 2024). "Upon activation by INF-DC, these cells secrete IL-8, tumor necrosis factor, and GM-CSF, thereby promoting the accumulation of immunosuppressive PMN-MDSCs and facilitating the progression of colon cancer." (PMID 39253082, 2024). "When colon cancer was induced with AOM/DSS, the expression of inflammation-related genes such as IL-1β, IL-6, and TNF in the blood increased, and the expression of inflammatory cytokines was confirmed in the serum of mice." (PMID 38338927, 2024). "HFD demonstrated higher IL-6 and TNFα expression in colonic tumors than ND; HFD, ND + Ex, and HFD + Ex showed higher GPR109A expression in colon tumors than ND." (PMID 38792787, 2024). "Transgenic expression of ALOX15 suppresses TNF-α and iNOS expression as well as NF-κB activation and downregulates LRP5 to suppress Wnt/β-catenin signaling, thereby inhibiting colon cancer." (PMID 39334689, 2024).
colon carcinoma (continued). "In vitro experiments with Lactobacillus reuteri BCRC14652 showed destruction of the cell membrane of colon cancer HT29 cells, inhibition of tumor necrosis factor (TNF) induced NF-κB activation, and suppression of cancer cells growth through apoptosis." (PMID 39021626, 2024). "that bs-Ab (TNF-α × CEA) against carcinoembryonic (CEA) and TNF-α enhances radiotherapy both in vivo and in vitro of colon cancer, particularly in tumors that overexpress CEA." (PMID 39609700, 2024). "The treatment with LXA4 reduced LPS-evoked TNF-α production and inhibited NF-κB activation in a coculture system using RAW264.7 cells and human colon carcinoma cell line (Caco-2)." (PMID 37388729, 2023). "The results of these assays revealed that human TNF-α (50 ng/mL) significantly inhibited proliferation of the HCT8, HCT116, and COLO205 colon cancer cell lines by 66%, 65%, and 54%, respectively, compared with controls." (PMID 37185713, 2023). "Several cytokines, including interleukin-6 (IL-6), tumor necrosis factor-alpha (TNF-α), and transforming growth factor-beta (TGF-β), have been identified as important regulators of colon cancer development and progression." (PMID 37465677, 2023). "A similar study showed that tectorigenin inhibited tumor necrosis factor-α (TNF-α) via NF-κB inhibition, thereby decreasing CXCL10 overproduction to hinder the invasion of Caco-2, which is a human colon cancer cell line." (PMID 37570873, 2023). "In the current study, we demonstrated that VIP antagonist enhanced M1 markers TNF-α, iNOS, and CXCL10, reduced Mrc-1 mRNA expression, and increased phagocytic ability against CT26 colon cancer cells in mouse macrophage RAW264.7 cells incubated with CT26-CM." (PMID 36650220, 2023). "Second, we used only one colon cancer cell line, CT26, and the effects of anti-TNFα mAb on other carcinomas and other colon cancer cell lines were not studied." (PMID 36996146, 2023). "Multiple inflammatory markers, such as tumor necrosis factor α (TNF-α), interleukin-6 (IL-6), and vascular endothelial growth factor (VEGF) have demonstrated prognostic value in patients with colon cancer." (PMID 37430251, 2023). "For example, in colon cancer, knockdown of HSPA13 accelerates apoptosis and necrosis, facilitating ubiquitination of RIP1 in response to TNFα induction." (PMID 38062023, 2023). "In particular, the pro-inflammatory cytokines tumor necrosis factor (TNF)-α and interferon (IFN)-γ exert growth-inhibitory effects on human colon cancer cells by triggering the onset of PANoptosis." (PMID 37662906, 2023). "In this study, we also found that the expression of GSDME-N in colon cancer cells treated with oxaliplatin was significantly increased, and the release of LDH and the content of TNF-α in the supernatant were significantly increased." (PMID 37658132, 2023). "previously treated mice with anti-PD-L1 therapy, they also showed an increase in TNF-α but, in contrast to our model, also of IFN-γ, which resulted in a therapeutic benefit in the MC38 colon carcinoma model." (PMID 35493461, 2022). "The functionality of Enbrel was confirmed by inhibiting prototypic necroptotic cell death induced by TNFα, the SMAC mimetic BV6 and the pan-caspase inhibitor zVAD.fmk (TBZ) in the human colon carcinoma cell line HT-29." (PMID 35408930, 2022). "Lactobacillus reuteri BCRC14652, tested in vitro, damaged the cell membranes of colon carcinoma HT29 cells, suppressed tumor necrosis factor (TNF)-induced NF-κB activation, and repressed the growth of cancer cells by apoptosis." (PMID 36144335, 2022). "The colon cancer group showed a marked increase in serum levels of CA19.9, CEA, AFP, TNF-α, IL-1β, and colon DNA-fragmentation matched with a decrease of CD4+ compared with the control group." (PMID 36294905, 2022).